TIMP4 (TIMP metallopeptidase inhibitor 4)
Diseases named in the same sentence as TIMP4 in open-access papers (continued):
Sharing a sentence is not in itself a finding about the gene and the disease.
amyloid (2 papers, 2023 to 2025). "Especially, our results suggest that sex-specific effects of these MMP-3 and TIMP-4 on amyloid pathology should be studied further." (PMID 37221606, 2023). "In contrast, amyloid-positivity was only significantly associated with reduced levels of MMP-3 and TIMP-4, and for these markers tau-positivity had a larger effect." (PMID 37221606, 2023). "Our findings show sex-specific effects of MMP-3 and TIMP-4 on amyloid pathology." (PMID 37221606, 2023).
aortic aneurysm (2 papers, 2019 to 2020). A ruptured aneurysm located in the wall of the proximal portion of the descending aorta proceeding from the arch of the aorta. "Increased TIMP4 expression has been reported in hyperhomocysteinemia-associated aortic aneurysm in humans and mice." (PMID 31857579, 2019). "Further, they found that VSMC deletion of BMAL1 led to upregulated levels of tissue inhibitor of metalloproteinase 4 (TIMP4), which revealed an intriguing interaction between these two proteins in the pathogenesis of aortic aneurysms." (PMID 32968712, 2020).
aortic stenosis (2 papers, 2020 to 2022). Aortic valve stenosis is a aortic valve disease caused by the incomplete opening of the aortic valve. "A study evaluating atrial remodeling in aortic stenosis patients with chronic AF showed a decrease in the MMP16/TIMP4 ratio in patients with AF along with an increased serum TIMP1 and TIMP2 proteins." (PMID 36312240, 2022). "This is the first study that suggests MMP16/TIMP4 as a marker of disease, specifically, a marker of chronic AF in aortic stenosis patients." (PMID 33129260, 2020).
Brain atrophy (2 papers, 2022 to 2024). Partial or complete wasting (loss) of brain tissue that was once present. "A global SVD score, expressed as a combined product of leukoaraiosis, lacunes, and brain atrophy, was associated with TIMP-4 levels at 90 days with a dose-response effect." (PMID 35408867, 2022).
brain tumor (2 papers, 2013 to 2024). "The protein expression of MMP9, MMP13, TIMP1, TIMP2, and TIMP4 was elevated in all three investigated brain tumor diagnoses." (PMID 38474106, 2024).
breast ductal carcinoma in situ (2 papers, 2013 to 2017). "Increased levels of TIMP-4 in BRCA tumors have been associated with tumor progression of ductal carcinoma in situ, and a shorter disease-free survival in BRCA patients, especially in estrogen receptor (ER)-negative tumors." (PMID 28545495, 2017).
chronic obstructive pulmonary disease (2 papers, 2019 to 2024). A chronic and progressive lung disorder characterized by the loss of elasticity of the bronchial tree and the air sacs, destruction of the air sacs wall, thickening of the bronchial wall, and mucous accumulation in the bronchial tree. "The purpose of this study was to compare matrix metalloproteinase-12 (MMP-12), neutrophil elastase (NE), and tissue inhibitor of metalloproteinase-4 (TIMP-4) in peripheral blood of patients with chronic obstructive pulmonary disease (COPD) and controls." (PMID 31143784, 2019).
Cognitive impairment (2 papers, 2023 to 2024). Abnormal cognition is characterized by deficits in thinking, reasoning, or remembering. "Increased levels of TIMP4 in blood have been associated previously with both cerebral small vessel disease (cSVD) and cognitive impairment." (PMID 38915119, 2024).
dyslipidaemia (2 papers, 2021). "Higher levels of TIMP-4 (p = 0.05) were observed in diabetic patients and higher levels of PINP (p < 0.05) were observed in patients diagnosed with dyslipidaemia." (PMID 34135421, 2021).
esophageal cancer (2 papers, 2018 to 2019). A primary or metastatic malignant neoplasm involving the esophagus. "Furthermore, DUXAP8 is positively related to MAGEA4, GABRA3 expression, and negatively related to INPP5A, TIMP4 expression in esophageal cancer; LINC00460 is positively related to ITGA3, LAMC2 expression, and negatively related to FOXO4, KLF15 expression in esophageal cancer." (PMID 29926523, 2018). "Similarly, we also found that knockdown of DUXAP8 could impair esophageal cancer cells proliferation and invasion, and DUXAP8 expression is positively related to oncogenes MAGEA4 and GABRA3 expression, but negatively related to tumor suppressors INPP5A and TIMP4." (PMID 29926523, 2018).
fatty liver (2 papers, 2017 to 2023). "In contrast to TIMP3, TIMP4 deficiency is protective against HFD-induced hepatic steatosis as demonstrated by the robust decrease in liver expression of the rate-limiting enzyme stearyl CoA desaturase 1 (Scd1) in TIMP4−/− mice compared with WT under a HFD." (PMID 37445827, 2023). "The protective effects of Timp4 gene deletion on hepatic steatosis could also be due to the decreased insulin levels in HFD-fed mice as insulin is a potent activator of hepatic lipogenesis." (PMID 28740132, 2017).
fibrosis (2 papers, 2013 to 2019). the formation of excess fibrous connective tissue in an organ or tissue in a reparative or reactive process. "TIMP1 and TIMP4 were both found to correlate inversely with suppressor of cytokine signaling 1 (SOCS1) expression in two in vitro fibrosis model systems and putatively shown to share CD63, an exosomal marker, as a binding partner in MMP-independent activities." (PMID 31765403, 2019). "Serum TIMP-4 and Endoglin showed highest values in HCV patients with liver cirrhosis compared to those with fibrosis but without cirrhosis." (PMID 23516586, 2013).
ischemic cardiomyopathy (2 papers, 2020 to 2022). Ischemic cardiomyopathy is a cardiomyopathy in which a weakness in the muscle of the heart due to inadequate oxygen delivery to the myocardium with coronary artery disease being the most common cause. "In the failing heart of patients with ischemic cardiomyopathy (ICM) or dilated cardiomyopathy (DCM), TIMP1 and TIMP3 levels were reduced with no change in TIMP2 and TIMP4, except TIMP4 protein decreased in ICM myocardium; however, myocardial levels of all four TIMPs were increased in another study." (PMID 32612540, 2020).
left ventricular hypertrophy (2 papers, 2022 to 2025). Enlargement of the LEFT VENTRICLE of the heart. "A plasma multibiomarker panel including TIMP-4 predicted the presence of diastolic heart failure in subjects with left ventricular hypertrophy, implicating TIMP-4 in extracellular matrix fibrillar collagen homeostasis." (PMID 35265689, 2022).
lipid metabolic disorders (2 papers, 2019 to 2024). "Therefore, we can speculate that TIMP4 may be involved in vasculitis formation, intravascular thrombosis and lipid metabolism disorders in hormone-mediated osteonecrosis of the femoral head." (PMID 30697482, 2019). "The reduction and inactivation of STAT3 lead to lipid metabolic disorders and promote triglyceride accumulation by upregulating the mRNA levels of ELOVL7, PPARG, MMP1, MMP13, and TIMP4, and downregulating the mRNA level of PTGS2." (PMID 39125712, 2024).
myopia (2 papers, 2023 to 2024). "Heterozygous LoF variants in the TIMP4 are associated with early onset high myopia, and the Timp4 defect disturbs ocular development by influencing the morphology and function of the ocular tissue." (PMID 38069250, 2023). "The association of TIMP4 deficiency and myopia was robustly supported by findings based on myopia patients and the gene editing rat model, but our study had several limitations." (PMID 38069250, 2023). "The alterations in collagen fiber structure in the Timp4-deficient rats may have implications for the biomechanical properties of the sclera, such as its tensile strength, elasticity, and resistance to deformation, which is closely related to myopia formation." (PMID 38069250, 2023). "Individuals with high myopia show upregulation of MMPs and TIMPs in the aqueous humor, while experiments in a rat model have suggested that knockout of TIMP4 can contribute to high myopia by reducing collagen content in the sclera and retina." (PMID 39759766, 2024). "The thinner retina was presented in a Timp4 dose-dependent manner, similar to other myopia gene-editing animal models." (PMID 38069250, 2023). "First, although the TIMP4 LoF variant enriched the HM population in our study, it was also detected in non-high myopia individuals and GenomAD." (PMID 38069250, 2023). "Since collagen is involved in myopia progression and is the target factor of TIMP4, we further evaluated the ocular tissues’ collagen to explore whether TIMP4 is related to a reduction in collagen content." (PMID 38069250, 2023). "Consequently, the Timp4 gene editing rat was further evaluated to explore the possible role of Timp4 on ocular and myopia development." (PMID 38069250, 2023). "This study identified two TIMP4 LoF variants of the TIMP4 in seven of 928 probands with early-onset high myopia, and the defect of the TIMP4 was significantly enriched in eoHM compared to 5469 non-myopia controls (p = 3.7 × 10−5) and the general population (p = 2.78 × 10−9)." (PMID 38069250, 2023). "In this study, the purpose of FD was to discover whether or not the ocular structure and function changes caused by the Timp4 defect in rats would be influenced by myopia-related pressure." (PMID 38069250, 2023). "This might explain why the LoF variants of the TIMP4 were not previously associated with high myopia in large cohorts." (PMID 38069250, 2023). "Two TIMP4 heterozygous loss-of-function (LoF) variants, c.528C>A in six patients and c.234_235insAA in one patient, were statistically enriched in 928 eoHM probands compared to that in 5469 non-high myopia control (p = 3.7 × 10−5) and that in the general population (p = 2.78 × 10−9)." (PMID 38069250, 2023). "The TIMP-4 efficiently inhibits the activity of MMP-2 via its N-terminus, and MMP2 upregulation was accompanied by significant myopia." (PMID 38069250, 2023).
osteoarthritis (2 papers, 2019 to 2025). A noninflammatory degenerative joint disease occurring chiefly in older persons, characterized by degeneration of the articular cartilage, hypertrophy of bone at the margins and changes in the synovial membrane. "TIMP4 was markedly decreased in cartilage samples of femoral heads obtained from patients with osteoarthritis (OA)." (PMID 40291774, 2025). "However, according to an osteoarthritis study by Huang, TIMP-4 gene expression is increased in the cartilage of the human femoral head." (PMID 30697482, 2019). "The expression of TIMP4 was markedly decreased in the cartilage of osteoarthritis patients." (PMID 30697482, 2019).
proliferative diabetic retinopathy (2 papers, 2022 to 2024). Advanced retinopathy due to diabetes mellitus characterized by the formation of new vessels in the retina. "These authors concluded that correlations between VEGF and MMP-9 and TIMP-4 were found more in the eye tissue for patients with proliferative diabetic retinopathy, which characterizes with increased neo-angiogenesis." (PMID 35655767, 2022).
rectal cancer (2 papers, 2014 to 2023). A primary or metastatic malignant neoplasm that affects the rectum. "TIMP4 is overexpressed in several cancers, including colorectal, and its expression was found to correlate with longer patient survival (in rectal cancer)." (PMID 37640106, 2023). "TIMP-4 is an inhibitor of MMP-2 catalytic activity; strong cytoplasmic staining of TIMP-4 in rectal cancer tissues predicted longer survival." (PMID 24518611, 2014).
renal cell carcinoma (2 papers, 2008 to 2021). "In studies on renal cell carcinomas (RCCs), TIMP4 showed opposite expression patterns in clear cell and papillary cell carcinomas." (PMID 34781885, 2021). "This is exemplified by renal cell carcinoma, in which TIMP-4 is elevated in papillary cancer cells, in contrast with clear cell carcinoma, in which TIMP-4 mRNA is reduced." (PMID 19025595, 2008).
systemic sclerosis (2 papers, 2008 to 2015). A chronic disorder, possibly autoimmune, marked by excessive production of collagen which results in hardening and thickening of body tissues. "Similarly, serum concentration of TIMP4 is increased in systemic sclerosis." (PMID 25978399, 2015).
tropical spastic paraparesis (2 papers, 2019 to 2025). "Moreover, upregulation of TIMP-4 in response to inflammation in CSF from patients with tropical spastic paraparesis or myelopathy associated with T cell lymphotropic virus was observed." (PMID 30062663, 2019).
acne (1 paper, 2024). An inflammatory process of the sebaceous glands which is characterized by comedones, nodules, papules and/or pustules on the skin. "Conversely, TIMP4 exhibited a positive β‐value of 0.157, linking higher genetically predicted levels of TIMP4 to an increased acne risk (OR = 1.169, 95% CI: 1.103–1.241, p = 1.956E‐07)." (PMID 39297226, 2024). "The colocalization results indicated a PH4 (probability of sharing the same causal variant) of 0.9323 for TIMP4, suggesting a high likelihood of sharing a common causal variant with acne risk." (PMID 39297226, 2024). "FASN exhibited a protective effect against acne (OR = 0.768, 95% CI: 0.676–0.872, p = 4.685E‐05), while TIMP4 was associated with an increased risk (OR = 1.169, 95% CI: 1.103–1.241, p = 1.956E‐07)." (PMID 39297226, 2024). "Following multiple testing corrections using the Benjamini–Hochberg method, fatty acid synthase (FASN) and tissue inhibitor of metalloproteinases 4 (TIMP4) remained significantly associated with acne risk." (PMID 39297226, 2024). "Existing research suggests that TIMP4 may be associated with the risk of acne by influencing sebaceous gland activity, inflammatory responses, tissue remodeling, and ECM degradation." (PMID 39297226, 2024). "More specifically, studies indicate that TIMP4 is present in the facial sebum of acne patients and that a decrease in TIMP4 expression following treatment with isotretinoin is associated with clinical improvement in acne." (PMID 39297226, 2024). "Following the application of the Benjamini–Hochberg (B–H) method for FDR correction set at 0.05, only two proteins, FASN fatty acid synthase (FASN) and tissue inhibitor of metalloproteinases 4 (TIMP4), remained significantly associated with acne risk." (PMID 39297226, 2024). "In the research exploring potential therapeutic targets for acne, through Mendelian randomization (MR) analysis and colocalization analysis, we identified two proteins significantly associated with acne risk: FASN and TIMP4." (PMID 39297226, 2024). "Despite the HEIDI test p value of 0.055 being slightly above the conventional threshold, the association remained significant post‐FDR correction (p = 3.33E‐04), indicating that the relationship between TIMP4 and acne risk is not driven by pleiotropy." (PMID 39297226, 2024). "Similar to TIMP4, FASN may also influence the risk of acne onset through pathways such as sebaceous gland activity and inflammatory responses." (PMID 39297226, 2024). "This suggests that TIMP4 in the sebum may be involved in the pathological process of acne, including its protective role on the ECM in scenarios of inflammation and abnormal keratinization." (PMID 39297226, 2024).
aneurysm (1 paper, 2015). Bulging or ballooning in an area of an artery secondary to arterial wall weakening. "We found comparable collagen-stained area between the groups, significantly decreased mRNA level of CTGF, osteopontin-1, and MMP-2, and increased TIMP-4 expression in aneurysms." (PMID 26539497, 2015). "Since TIMP-4 is an important counter actor for MMP-2 in achieving a balanced matrix turnover, we assume that the observed difference in MMP-2/TIMP-4 ratio reflects this balance in our aneurysm patients." (PMID 26539497, 2015).
asthma (1 paper, 2025). "The combined model incorporating seven features, past asthma attacks, Capnocytophaga, Corynebacterium, and Cardiobacterium, TIMP-4, VEGF, and MIP-3β achieved the highest accuracy with AUROCC ~0.87." (PMID 40823900, 2025).
benign prostatic hyperplasia (1 paper, 2022). A non-cancerous nodular enlargement of the prostate gland. "Correspondingly, several other studies have reported an increased expression of hsa-miR-200b-3p in PCa compared with that in benign prostatic hyperplasias, as well as a positive correlation with TIMP4, which is an inhibitor of MMP2." (PMID 36232996, 2022).
cardiac arrest (1 paper, 2025). Cessation of breathing and/or cardiac function. "When extracting proteins unlikely to show post-cardiac arrest changes based on their levels in relation to lactate and sampling time, two proteins (AXL and TIMP-4) were identified." (PMID 39992996, 2025).
cardiomyopathy (1 paper, 2010). A disease of the heart muscle or myocardium proper. "The mitigation of cardiomyopathy by tempol is reinforced by attenuation of MMP-9, TIMP-3 and induction of TIMP-4." (PMID 20828387, 2010).
cerebral small vessel disease (1 paper, 2024). Cerebral small vessel disease is the term currently used to pathological processes that affect the brain parenchymal circulation (arterioles, capillaries, and veins). "This suggests that TIMP4 may be involved in the pathological processes of various forms of cerebral small vessel disease, with either amyloidogenic or ischemic cause." (PMID 38915119, 2024).
cholangiocarcinoma (1 paper, 2015). A carcinoma that arises from the intrahepatic biliary tree (intrahepatic cholangiocarcinoma) or from the junction, or adjacent to the junction, of the right and left hepatic ducts (hilar cholangiocarcinoma). "In addition, RKIP significantly enhanced TIMP-4 gene expression, playing a complementary role in suppressing cholangiocarcinoma cell invasion." (PMID 25435928, 2015). "RKIP is negatively associated with cholangiocarcinoma distant metastasis and prevents cholangiocarcinoma cell metastasis through downregulating MMP-9 expression and upregulating TIMP-4 expression." (PMID 25435928, 2015). "RKIP inhibited the invasive and metastatic ability of the cholangiocarcinoma cell line, RBE, by downregulating MMP-9 and upregulating TIMP-4 mRNA expression." (PMID 25435928, 2015). "In the present study, RKIP was revealed to inhibit the invasion and metastasis of cholangiocarcinoma cells by downregulating MMP-9, but upregulating TIMP-4 mRNA expression." (PMID 25435928, 2015). "RKIP inhibits cholangiocarcinoma cell invasion and migration via downregulating MMP-9 expression and upregulating TIMP-4 expression." (PMID 25435928, 2015).
cholestasis (1 paper, 2013). Impairment of the bile flow caused by obstruction within the liver, or outside the liver in the bile duct system. "Further, when clinical cholestasis markers were compared with the novel modalities for CFLD diagnosis assessed in this report, Bland-Altman Analyses revealed the presence of a proportional error in the agreement of γGT and the biomarkers TIMP-4 and Endoglin and in the agreement of ALP and TE." (PMID 23516586, 2013).
Crohn disease (1 paper, 2008). A gastrointestinal disorder characterized by chronic inflammation involving all layers of the intestinal wall, noncaseating granulomas affecting the intestinal wall and regional lymph nodes, and transmural fibrosis. "TIMP-1, TIMP-2 and TIMP-4 serum levels were determined in 53 patients with ulcerative colitis (UC), 52 patients with Crohn's disease (CD) and 50 HC, by means of commercially available enzyme-linked immunosorbent assays." (PMID 19036126, 2008).
cystic fibrosis (1 paper, 2013). Autosomal recessive disorder caused by pathogenic variants in the CFTR gene (cystic fibrosis transmembrane conductance regulator), which encodes a chloride and bicarbonate channel expressed in epithelial cells, and follow the diagnosis criteria. "In this report, we now show that TIMP-4 as a previously rather unrecognized member of the TIMP-family is significantly increased in cystic fibrosis associated liver disease." (PMID 23516586, 2013).